SMARCB1 (SWI/SNF related BAF chromatin remodeling complex subunit B1)
Diseases named in the same sentence as SMARCB1 in open-access papers (continued):
Sharing a sentence is not in itself a finding about the gene and the disease.
squamous cell carcinoma (11 papers, 2013 to 2026). A carcinoma arising from squamous epithelial cells. "We demonstrated squamous cell carcinoma of that pleura which was characterized by SMARCB1 deficiency." (PMID 29625594, 2018). "Herein, we reports the first case of SMARCB1-deficient squamous cell carcinoma of the pleura whose prognosis was poor as with another SMARCB1 deficient tumors." (PMID 29625594, 2018). "We report the first case of SMARCB1-deficient squamous cell carcinoma of the pleura in a patient." (PMID 29625594, 2018). "This is the first report of SMARCB1-deficient squamous cell carcinoma of pleura." (PMID 29625594, 2018). "We report the first case of SMARCB1- deficient squamous cell carcinoma of the pleura." (PMID 29625594, 2018). "Following this report, we estimated that the rate of SMARCB1 deficits in extrasinonasal squamous cell carcinomas in the head and neck region is approximately 0.6%." (PMID 39398818, 2024). "The loss of expression of the protein SMARCB1/INI1 characterizes ES but it has never been described in either squamous cell carcinomas or adnexal skin neoplasms." (PMID 23691400, 2013). "This study elucidates the aggressive nature of SMARCB1-deficient squamous cell carcinoma (SqCC) in never smokers, highlighting a significant impact on disease-free survival and underscoring the urgent need for advanced molecular diagnostics and targeted therapies." (PMID 39125735, 2024). "NET G3, on the other hand, was suggested as diagnosis in 10 NETs G2, 5 NECs, 7 MiNENs, and various other carcinomas including medullary thyroid carcinoma, adenocarcinoma, squamous cell carcinoma, acinar cell carcinoma, and SMARCB1-deficient neoplasm (data not shown)." (PMID 34499237, 2022). "Next, n = 116 samples of patients with pure squamous cell carcinoma (n = 68) and mixed urothelial carcinoma with substantial squamous differentiation (n = 48) were analyzed for seven SWI/SNF complex proteins (ARID1A, SMARCA4, SMARCB1, SMARCC1, SMARCC2, SMARCA2 and PBRM1) by immunohistochemistry." (PMID 33227989, 2020).
T-cell lymphomas (11 papers, 2015 to 2025). "We pharmacologically examined the extent to which the T-cell lymphomas that emerge upon conditional loss of SMARCB1 (SNF5) are MCL-1 dependent." (PMID 41309546, 2025). "In a mouse tumor model, a reversible conditional Smarcb1 allele causes the majority of mice to develop a mature T-cell lymphoma within a few weeks upon loss of Smarcb127." (PMID 39362842, 2024). "Thereby, the optimal k value that allows splitting Mb and Nb also defined three tumour groups within Smarcb1-deficient tumours: CD8(+)T-cell lymphomas and two other subgroups." (PMID 26818002, 2016). "By analyzing SMARCB1 RNA and protein expression levels in multiple subtypes of mature T-cell lymphomas, we could exclude T-PLL, MEITL, EATL, MF, AITL and ALK-negative ALCL being the human counterpart of the phenotype observed in Smarcb1-deficient mice." (PMID 39362842, 2024). "As we did not detect common loss of SMARCB1 expression in T-PLL, MF, EATL and MEITL, these entities do not appear to be the human counterpart to the mature T-cell lymphomas in the Smarcb1-deficient mouse model." (PMID 39362842, 2024).
undifferentiated carcinoma (11 papers, 2020 to 2024). A usually aggressive malignant epithelial neoplasm composed of atypical cells which do not display evidence of glandular, squamous, or transitional cell differentiation. "We describe an uncommon case of a middle-aged man presenting with SMARCB1-deficient undifferentiated carcinoma." (PMID 38217014, 2024). "The final pathological diagnosis was SMARCB1‐deficient undifferentiated carcinoma, pT3N2bM0 (Stage IIIc), according to the World Health Organization classification of digestive system tumors, 5th edition." (PMID 38217014, 2024). "SMARCB1-deficient undifferentiated carcinoma in the rectum is extremely rare, and it has aggressive histological malignancy and poor progression." (PMID 38217014, 2024). "Here, we report the first case of a SMARCB1-deficient undifferentiated carcinoma expressing high PD-L1 and responding to a PD-1 inhibitor, with low tumor mutation burden (TMB), proficient mismatch repair (MMR) and BRAF V600E mutation in the rectum." (PMID 38217014, 2024). "Here, we report the first case of a SMARCB1-deficient undifferentiated carcinoma in the rectum expressing high PD-L1 and responding to a PD-1 inhibitor, as well as with low tumor mutation burden (TMB), proficient mismatch repair (MMR) and BRAF V600E mutation." (PMID 38217014, 2024). "The final diagnosis was SMARCB1-deficient undifferentiated carcinoma." (PMID 38217014, 2024). "Research of SMARCB1 deletion should be performed for undifferentiated carcinomas of young patients because of the possibility of molecular therapy, such as autophagy inhibitors or proteasome inhibitors, in clinical trials." (PMID 37974295, 2023). "SMARCB1 deletion in this unusual situation of undifferentiated carcinoma should be completed because of the opportunity to offer new treatments." (PMID 37974295, 2023). "SMARCA4-deficiency was mostly found in teratocarcinosarcoma while SMARCB1-deficient tumors were associated with undifferentiated carcinoma and non-keratinizing squamous cell carcinoma." (PMID 36937407, 2023). "Except for 2 cases with undifferentiated carcinoma, SMARCB1-attenuated GC could be a tubular or poorly cohesive carcinoma." (PMID 33481850, 2021). "For SMARCB1-attenuated GCs, only 2 of 11 cases were undifferentiated carcinoma." (PMID 33481850, 2021). "SMARCB1 or SMARCA4 loss was not restricted to rhabdoid/undifferentiated carcinoma." (PMID 33481850, 2021).
Ewing sarcoma (10 papers, 2014 to 2025). A small round cell tumor that lacks morphologic, immunohistochemical, and electron microscopic evidence of neuroectodermal differentiation. "A total of 13/31 (42%) of the MN-NE showed EWSR1-related gene fusions (6 Ewing sarcomas, 5 clear cell sarcomas, and 1 desmoplastic small round cell tumor, 1 neoplasm with FUS-CREM gene fusion) and 7 (23%) were SWI/SNF (SMARCB1 or SMARCA4)-deficient neoplasms." (PMID 34350470, 2021). "The most frequent initial misdiagnosis was Ewing’s sarcoma, instead of myxoid liposarcoma (FUS-DDDIT3), rhabdoid soft tissue tumor (SMARCB1), or angiomatoid fibrous histiocytoma (EWSR1-CREB1)." (PMID 34771600, 2021).
extraskeletal myxoid chondrosarcoma (10 papers, 2013 to 2024). A rare malignant soft tissue neoplasm of uncertain differentiation, characterized by the presence of chondroblast-like cells in a myxoid stroma and a multinodular growth pattern. "This suggested that these last tumors were definitely not RT, but behaved also differently from ES, RMC and UC, being either known SMARCB1-deficient entities not included in our training set (eMPNST, extra-skeletal chondrosarcomas, etc...), or unknown other entities." (PMID 28427232, 2017).
soft tissue tumors (10 papers, 2018 to 2026). "Among these, SMARCB1/INI1 emerges as a frequent target of inactivating mutations in soft tissue tumors, where its loss disrupts critical tumor suppressor pathways." (PMID 41317331, 2026). "The mosaic expression of SMARCB1 has been reported in soft tissue tumors as a diagnostic tool and a parameter of morphological aggressiveness." (PMID 39590317, 2024). "SMARCB1-deficient soft tissue neoplasms traditionally comprise of a monomorphic population of undifferentiated epithelioid cells with “prototypical” rhabdoid cytomorphology, and anaplastic large-cell or small round-cell features." (PMID 38236556, 2024). "Aberrant expression of SMARCB1 has been found in a variety of tumors, such as pancreatic rhabdoid carcinoma, yolk sac tumors thoracic neoplasms, soft-tissue neoplasms and renal cancer." (PMID 40115023, 2025). "In the sinonasal tract, deficiencies of the subunits SMARCB1/INI1, SMARCA4/BRG1, and SMARCA2 have been noted in carcinomas, adenocarcinomas, and soft tissue tumors with a distinctive high-grade morphology and a fatal prognosis." (PMID 39590317, 2024). "Inactivating mutations in the SMARCB1 (INI1) and SMARCB4 genes were recently described in a subset of soft tissue tumors with epithelioid or rhabdoid cell features." (PMID 32316685, 2020). "However, it is now known that epithelial tumors, except soft tissue tumors, also exhibit deficits in SMARCB1." (PMID 39398818, 2024). "In soft tissue neoplasms, SMARCB1 (INI1) is the subunit most frequently inactivated, followed by SMARCA4 (BRG1), and SMARCA2." (PMID 35125107, 2022).
BAFopathy (9 papers, 2021 to 2024). Disorder caused by mutations in the various subunits composing the BAF complex. "Typical CSS, which is also referred to as BAFopathy, is caused by variants in the subunit of BAF complex, including ARID1A (OMIM#603024), ARID1B (OMIM#614556), SMARCA4 (OMIM#603254), SMARCB1 (OMIM#601607), ARID2 (OMIM#609539), and SMARCE1 (OMIM#603111)." (PMID 35938035, 2022). "Studies have shown that DNAm profiles at subsets of CpGs overlap between individuals with BAFopathies carrying variants in SMARCA2 that cause NCBRS, and in ARID1B, SMARCB1, and SMARCA4 that lead to Coffin-Siris syndromes type 1, 3, and 4, respectively." (PMID 35361921, 2022). "Among the most prominent and most studied BAFopathies are the clinically overlapping syndromes CSS and Nicolaides-Baraitser (NCBRS) (MIM: 601358), caused by variants in BAF complex proteins: ARID1B in CSS1, SMARCB1 in CSS2, and SMARCA4 in CSS4; and SMARCA2 in NCBRS." (PMID 38751117, 2024). "Other combined episignatures, such as for the BAFopathy (genes: ARID1A, ARID1B, SMARCB1, SMARCA2 and SMARCA4) episignature, are already proving their clinical utility." (PMID 38787418, 2024). "We detected a predominantly hypermethylation profile; the highest percentage of overlap in DMPs was with BAFopathies (11%, including ARID1A, ARID1B, SMARCB1, SMARCA2, SMARCA4), and CHARGE syndrome (10%, CHD7)." (PMID 38351292, 2024). "BAFopathy presented with a ~4% overlap, including ARID1A, ARID1B, SMARCB1, SMARCA2, and SMARCA4, and includes several neurodevelopmental disorders caused by variants in genes within the BRG1/BRM-associated factor (BAF) complex." (PMID 37762546, 2023). "This analysis showed that TRIP12 is most closely related to the CSS9 (SOX11), BAFopathy (ARID1A, ARID1B, SMARCB1, SMARCA2, SMARCA4) and MRD23 (SETD5) episignatures." (PMID 36430143, 2022). "Notably, JARID2 exhibited the highest overlap with CHARGE (~7%, CHD7), BAFopathy (~4%, including ARID1A, ARID1B, SMARCB1, SMARCA2, SMARCA4), and the PCR2 complex, which houses Cohen–Gibson syndrome (COGIS) and Weaver syndrome (WVS) (~4%, EED, EZH2)." (PMID 37762546, 2023).
glioblastoma (9 papers, 2014 to 2025). The most malignant astrocytic tumor (WHO grade IV). "Although mutations in the SMARCB1 gene are found in only 2–3% of glioblastoma cases, studies suggest these mutations are linked to an earlier disease onset." (PMID 40564017, 2025). "SMARCB1 is also known as INI1, whose downregulation is associated with aggressive behavior of glioblastoma." (PMID 32420340, 2020). "Another patient (case 3) diagnosed with a histopathologically confirmed SMARCB1 nucleopositive glioblastoma within the irradiation field as secondary tumor 9.5 years after diagnosis of his ATRT is also alive." (PMID 24402832, 2014). "While the relationship between SMARCB1 mutations and glioblastoma prognosis is not well researched, SMARCB1 loss has been identified in several rare pediatric and adult cancers, termed SMARCB1-deficient cancers, most of which have a poor prognosis." (PMID 40564017, 2025). "Expressions of lncRNA-MEG3 and SMARCB1 were detected in human glioblastoma U87 and U251 cell lines." (PMID 32420340, 2020).
breast carcinoma (8 papers, 2010 to 2025). "ARID1A and SMARCB1 inactivation have recently been shown to reduce the sensitivity of breast cancer cells to estrogen receptor inhibition, giving support to our findings in a second cancer type." (PMID 37554444, 2023). "Finally, the use of OncoScantm has allowed us to detected mutations in five genes that have not been shown to be mutated in TCGA subset of Her-2 overexpressing breast cancer: CTNNB1, HRAS, KRAS, NF2 and SMARCB1." (PMID 28247034, 2017). "One set that was present in their data set after SMARCB1 reactivation and in 2 of our cell lines, CHLA02 and CHLA05, after combination treatment was “WANG_SMARCE1_TARGETS_UP,” which represents genes that are upregulated in breast cancer with reintroduction of SMARCE1, another component of SWI/SNF." (PMID 41408661, 2025).
collecting duct carcinoma (8 papers, 2016 to 2025). "The collecting duct carcinoma and SMARCB1 deficient medullary RCC were rare tumors in our consultation cohort." (PMID 34680535, 2021). "In contrast to collecting duct carcinomas, these tumours may express OCT3/4 on immunohistochemistry and show loss of expression of SMARCB1 (INI1)." (PMID 30123932, 2018).
ovarian carcinoma (8 papers, 2015 to 2025). A malignant neoplasm originating from the surface ovarian epithelium. "In addition to these genes, a high risk for ovarian cancer is associated with mutations in the DICER1, VHL, PTCH1, SUFU, SMARCB1, and SMARCA4 genes." (PMID 37685988, 2023).
developmental delay (7 papers, 2017 to 2025). "Similarly, consistent with previous publications, individuals with SMARCB1 variants were found to have significantly greater developmental delays compared to other groups." (PMID 34205270, 2021).
extrarenal rhabdoid tumor (7 papers, 2015 to 2023). A rhabdoid tumor which arises in the soft tissues. "Malignant SMARCB1/INI1-deficient extrarenal rhabdoid tumors are aggressive neoplasms that are extremely rare in adults." (PMID 32467817, 2020). "Malignant SMARCB1/INI1-deficient extrarenal rhabdoid tumors are aggressive tumors that are extremely rare in adults." (PMID 32467817, 2020). "The variants identified in SMARCB1 in two different patients with soft tissue rhabdoid tumors were not identified in the germline, thus confirming their somatic origin." (PMID 36805510, 2023).
kidney cancer (7 papers, 2017 to 2025). Primary or metastatic malignant neoplasm involving the kidney. "Although rare, RMC is the third most common kidney cancer among adolescents and young adults, comprising the vast majority of SMARCB1-deficient renal malignancies, and predominantly afflicting young individuals of African descent who harbor the sickle cell trait." (PMID 41290625, 2025). "786-O, ACHN, and CAL54 had perfect agreement on CNAs in key kidney cancer genes, while 769-P had only one disagreement (SMARCB1 is amplified in CCLE but diploid in CCLP)." (PMID 28489074, 2017). "Since there are no SMARCB1 wildtype pediatric kidney cancer cell lines in CCLE, we compared the sensitivity to bortezomib or MLN2238 in our RMC models with wildtype SMARCB1 patient-derived Wilms tumor cell line, CLF_PEDS1012_T." (PMID 30860482, 2019). "Although we did not detect any differentially methylated loci at the SMARCB1 locus on chromosome 22, we did observe an enrichment of SCT-associated DMPs at 15 CpG sites previously associated with clear cell renal carcinoma (a more common type of kidney cancer)." (PMID 40758858, 2025).
Kleefstra syndrome (7 papers, 2014 to 2025). A genetic disorder characterized by intellectual disability, childhood hypotonia, severe expressive speech delay and a distinctive facial appearance with a spectrum of additional clinical features. "In addition, pathogenic de novo variants in MBD5 and in other epigenetic regulators (SMARCB1, NR1I3, KMT2C) were reported in individuals with a clinical diagnosis of Kleefstra syndrome (KS; OMIM #610253)." (PMID 35205380, 2022). "In addition to EHMT1 mutations, de novo variants were reported in four additional genes (MBD5, SMARCB1, NR1I3, and KMT2C), in single individuals with clinical characteristics overlapping Kleefstra syndrome." (PMID 29069077, 2017).
lung adenocarcinoma (7 papers, 2013 to 2026). A carcinoma that arises from the lung and is characterized by the presence of malignant glandular epithelial cells. "Lung adenocarcinoma patients with WSE showed a distinctive mutated profile for the SMARCB1, ATM, EGFR exon 7, RET and KDR genes." (PMID 30093964, 2018). "For this, we made use of a GR activity score (explained above) and the lung adenocarcinoma dataset from TCGA (91/877 tumours harboured SWI/SNF mutations; SMARCB1 18.09%; SMARCC2 9.52%, SMARCD2 6.66%, SMARCD3 1.90%, ARID1A 29.52%, ARID2 31.42%, SMARCE1 2.85%)." (PMID 34272384, 2021). "On this study we describe a landscape of genomic alterations in lung adenocarcinoma patients with WSE in the tumor suppressors SMARCB1 and ATM, in addition to the oncogenes EGFR, RET and KDR." (PMID 30093964, 2018). "We hypothesize that carcinogens released by WSE produce frameshift truncations, resulting in loss of protein function in the tumor suppressors ATM and SMARCB1, and subsequent mutations in the oncogenes RET, KDR and EGFR exon 7 among others involved in the development of lung adenocarcinoma." (PMID 30093964, 2018).
neurofibroma (7 papers, 2013 to 2024). An intraneural or extraneural neoplasm arising from nerve tissues and neural sheaths. "Molecular analysis of a resected cervical spine schwannoma-neurofibroma demonstrated an isolated somatic SMARCB1 mutation." (PMID 38058737, 2023). "The pathology demonstrated a mixed schwannoma-neurofibroma, and sequencing identified a SMARCB1 mutation with wild-type NF2 gene." (PMID 38058737, 2023).
neurofibromatosis (7 papers, 2021 to 2025). A hereditary neoplastic syndrome in which tumors grow in the nervous system. "Mutations in the SMARCB1 (otherwise known as INI1, BAF47, or hSNF5 gene and centromeric to the NF2 gene situated on chromosome 22) and LZTR1 genes (also located on chromosome 22, close to the former gene), which suppress tumors, are associated with this type of neurofibromatosis." (PMID 35053664, 2022). "Here, the authors report a rare case of a 2-year-old boy with a SMARCB1 (INI1) retained but SMARCA4 (BRG1) negative AT/RT arising at the bilateral cerebellopontine angles mimicking neurofibromatosis type 2." (PMID 34611487, 2021).
urothelial carcinoma (7 papers, 2019 to 2025). A malignant neoplasm derived from the transitional epithelium of the urinary tract (urinary bladder, ureter, urethra, or renal pelvis). "Compared to conventional urothelial carcinoma, tumours with complete loss of SMARCB1 exhibit lower mutation burden, single nucleotide variant, and copy number variant frequencies." (PMID 39779467, 2025). "Differential diagnosis of CDC includes urothelial carcinoma arising from the renal pelvis and SMARCB-1 deficient medullary-like renal carcinoma (SD-MLC)." (PMID 38957193, 2023). "We saw a significant decrease in cell viability in SMARCB1 deficient cell lines as compared to urothelial carcinoma cell line, JMSU1 (SWI/SNF wild type), or non-small cell lung cancer cell line, A549 (SMARCA4 mutant) (two-tailed t-test p-values 4.5e-5 and 4.6e-5)." (PMID 30860482, 2019). "Future studies should investigate the possibility that polygenic germline interactions may influence SMARCB1 expression in urothelial carcinomas." (PMID 38355560, 2024).